ENSG00000302938 (novel transcript)
Gene: Long non-coding RNA gene on chromosome 1 (210,374,135 to 210,374,273, reverse strand). Ensembl gene ENSG00000302938.
Gene Ontology:
Biological process: formation of quadruple SL/U4/U5/U6 snRNP; spliceosomal tri-snRNP complex assembly
Cellular component: U4/U6 x U5 tri-snRNP complex; U5 snRNP